STMN3 (stathmin 3)
Description:
Exhibits microtubule-destabilizing activity, which is antagonized by STAT3.
Synonyms: SCLIP
Tractability: PROTAC: ubiquitination databases record sites on it.
Gene: Protein-coding gene on chromosome 20 (63,639,705 to 63,657,682, reverse strand). Ensembl gene ENSG00000197457.
Subcellular location: Golgi apparatus; Cell projection, growth cone; Cell projection, axon; Cytoplasm, cytosol
Subcellular location (Human Protein Atlas): Golgi apparatus; Cytosol
Gene Ontology:
Molecular function: protein binding; protein domain specific binding; tubulin binding
Biological process: cytoplasmic microtubule organization; microtubule depolymerization; negative regulation of neuron projection development; negative regulation of Rac protein signal transduction; nervous system development; neuron projection development; regulation of cytoskeleton organization; regulation of microtubule polymerization or depolymerization
Cellular component: Golgi apparatus; cytoplasm; cytosol; neuron projection; axon; growth cone
Genetic constraint (gnomAD): Loss-of-function variants: 24 observed, 17.46 expected, observed/expected ratio (o/e) 1.37, 90% interval 0.99 to 1.85. The synonymous counts are far from expectation, so gnomAD's model fits this gene poorly and the ratio says little. Missense variants: 235 observed, 186.79 expected, observed/expected ratio (o/e) 1.26, 90% interval 1.13 to 1.4. Synonymous variants: 117 observed, 80.57 expected, observed/expected ratio (o/e) 1.45, 90% interval 1.25 to 1.69.
Homologues: Orthologues: chimpanzee STMN3 (97% identical), macaque STMN3 (97% identical), guinea pig STMN3 (96% identical), mouse Stmn3 (96% identical), pig STMN3 (96% identical), dog STMN3 (95% identical), tropical clawed frog stmn3 (81% identical), zebrafish stmn3 (67% identical), rat Stmn3 (54% identical), Drosophila melanogaster stai (38% identical). Paralogues in human: STMN2 (73% identical), STMN4 (61% identical), STMN1 (52% identical), STMND1 (25% identical).
Diseases named in the same sentence as STMN3 in open-access papers:
STMN3 is named in the same sentence as 16 diseases in open-access papers, as found by Europe PMC text mining. Sharing a sentence is not in itself a finding about the gene and the disease. The quoted sentences say what the papers report.
glioma (6 papers, 2016 to 2025). A benign or malignant brain and spinal cord tumor that arises from glial cells (astrocytes, oligodendrocytes, ependymal cells). "We provide evidence that rs3761124 is a functional variant on 20q13.33 related to glioma/GBM risk that modulates the expression of STMN3 and potentially other genes across diverse cellular contexts." (PMID 33169458, 2021). "We further show that this SNP affects glioma risk potentially through the altered expression of STMN3, RTEL1, GMEB2, and several other genes based on CRISPR deletion of the risk enhancer." (PMID 33169458, 2021). "This latter cohort included several genes relevant to progenitor development and migration, including Arx, Dbx2, the semaphorin receptor plexin B3, and the cytoskeletal adaptor Stmn3, which has recently been linked to glioma motility." (PMID 27213272, 2016). "Intriguingly, our analysis instead implicates STMN3 at 20q13.33, whose over-expression promotes growth in GBM cells, suggesting an alternative mechanism by which the risk SNP influences glioma development." (PMID 29460007, 2018). "Finally, our tissue-specific analyses highlight five candidate tissues (cerebellum, cortex, and the putamen, caudate and nucleus accumbens basal ganglia) and four genes (JAK1, STMN3, PICK1 and EGFR) which had causal evidence for affecting glioma risk in further research." (PMID 33504897, 2021). "In addition to our own finding, the importance of STMN3 in glioma is supported by other studies." (PMID 33169458, 2021). "Among 55 adult tissues analyzed through GTEx, the STMN3 expression is the highest in the 13 CNS tissues (GTEX portal access 18 June, 2020); furthermore, messenger RNA (mRNA) and protein of this gene are overexpressed in human glioma of all grades as compared with normal brain tissues." (PMID 33169458, 2021). "Therefore, STMN3 is a consistent eQTL for rs3761124 in early neurological development, in the normal adult brain and in glioma or during gliomagenesis, whereas the RTEL1 expression correlated with rs3761124 only during early neurological development and in IDH1 wild‐type glioma." (PMID 33169458, 2021).
non-small cell lung carcinoma (2 papers, 2014 to 2023). A group of at least three distinct histological types of lung cancer, including non-small cell squamous cell carcinoma, adenocarcinoma, and large cell carcinoma. "The substantial expression of STMN3 in most tissues point out a novel function for this protein outside the nervous system and raises the possibility that modulation of STMN3 could promote nicotine mediated induction of non-small cell lung cancer progression and metastasis." (PMID 25028095, 2014). "Similarly, STMN3, a microtubule destabilizing protein, is induced by both nicotine and EGF in an ID1 dependent fashion, as well as can facilitate the proliferation, invasion and migration of non-small cell lung cancer." (PMID 37965307, 2023).
bladder cancer (1 paper, 2023). "As is well known, nicotine is the major ingredient of cigarette smoke, and smoking is the primary risk factor for bladder cancer, this might be the reason why STMN3 is highly expressed in the high-risk group of the model constructed by us." (PMID 37965307, 2023).
glioblastoma (1 paper, 2021). The most malignant astrocytic tumor (WHO grade IV). "The overexpression of STMN3 increased growth and mobility of glioblastoma cells, whereas STMN3 knockdown impaired cell growth, proliferation, invasion, and migration." (PMID 33169458, 2021).
lung carcinoma (1 paper, 2014). "The finding that STMN3 gene is a downstream target of the ID1, and responds to signaling from nAChRs and EGFR in lung cancer cells is relevant for various reasons." (PMID 25028095, 2014).
neuropathies (1 paper, 2021). "To examine whether the downregulation of STMNs is indeed responsible for the neuropathies of Trrap deleted neurons, we ectopically expressed STMN3 in Trrap knockdown neurons." (PMID 33594975, 2021).
pancreatic cancer (1 paper, 2022). "One down-regulated gene (STMN3) was further identified and significantly associated with the overall survival of pancreatic cancer patients." (PMID 35410237, 2022).
rectal cancer (1 paper, 2008). A primary or metastatic malignant neoplasm that affects the rectum. "On basis of integrative analysis this study identified one well known CRC gene (SMAD2) and several other genes (EFNA1, BOP1, TGIF2 and STMN3) that possibly could be used for rectal cancer characterization." (PMID 18959792, 2008). "We identified one well known CRC gene (SMAD2) and several other genes (EFNA1, BOP1, TGIF2 and STMN3) that possibly could be used for rectal cancer characterization." (PMID 18959792, 2008).
squamous cell carcinoma (1 paper, 2014). A carcinoma arising from squamous epithelial cells. "STMN3 is over-expressed in adenocarcinoma as well as squamous cell carcinoma (SCC) samples and STMN3 promoted cell proliferation, migration, and invasion." (PMID 25028095, 2014). "Co-expression of STMN3 and stathmin induced cell proliferation, migration, and matrix invasion in adenocarcinoma as well as squamous cell carcinoma tissues and reduced stathmin and STMN3 levels affected cell morphology and is associated with a less malignant phenotype." (PMID 25028095, 2014).
tumor (4 papers, 2012 to 2025). "Other genes, including MYB proto-oncogene like 2 (MYBL2), cyclin dependent kinase inhibitor 2A (CDKN2A), and stathmin 3 (STMN3) were significantly upregulated in tumor tissues from CRC patients and were significantly associated with specific bacterial genera." (PMID 40313460, 2025). "These tumor-promoting functions of ID1 appear to be brought about by STMN3 and GSPT1, which are up regulated by ID1." (PMID 25028095, 2014).
cancer (2 papers, 2022 to 2023). A tumor composed of atypical neoplastic, often pleomorphic cells that invade other tissues. "On the contrary, we noted the expression level of STMN3 was positively associated with resistance to cancer immunotherapy (anti-PD-1/PD-L1) in the Imvigor210 and GSE176307." (PMID 37965307, 2023).
STMN3 also shares sentences with these, for which no sentence is quoted: adenocarcinoma (1 paper); Cervical (1); melanoma (1); non-Hodgkin lymphoma (1); skin papilloma (1).